CBL (Cbl proto-oncogene)
Description:
E3 ubiquitin-protein ligase that acts as a negative regulator of many signaling pathways by mediating ubiquitination of cell surface receptors. Accepts ubiquitin from specific E2 ubiquitin-conjugating enzymes, and then transfers it to substrates promoting their degradation by the proteasome. Recognizes activated receptor tyrosine kinases, including KIT, FLT1, FGFR1, FGFR2, PDGFRA, PDGFRB, CSF1R, EPHA8 and KDR and mediates their ubiquitination to terminate signaling. Recognizes membrane-bound HCK, SRC and other kinases of the SRC family and mediates their ubiquitination and degradation. Ubiquitinates EGFR and SPRY2. Involved in LAG3-mediated inhibition of TCR signaling: following ligand-binding to LAG3, catalyzes 'Lys-63'-linked ubiquitination of LAG3, unleashing the LAG3 C-terminus from the membrane, and initiating a signaling that prevents TCR activation. Ubiquitinates NECTIN1 following association between NECTIN1 and herpes simplex virus 1/HHV-1 envelope glycoprotein D, leading to NECTIN1 removal from cell surface. Participates in signal transduction in hematopoietic cells. Plays an important role in the regulation of osteoblast differentiation and apoptosis. Essential for osteoclastic bone resorption. The 'Tyr-731' phosphorylated form induces the activation and recruitment of phosphatidylinositol 3-kinase to the cell membrane in a signaling pathway that is critical for osteoclast function. In association with CBLB, required for proper feedback inhibition of ciliary platelet-derived growth factor receptor-alpha (PDGFRA) signaling pathway via ubiquitination and internalization of PDGFRA (By similarity).
Synonyms: CBL2; RNF55; c-Cbl; FRA11B; NSLL
Tractability: Small molecule: it has a binding pocket of medium quality. Antibody: its Gene Ontology location is reachable by antibodies, with high confidence; UniProt places it where antibodies can reach, with medium confidence. PROTAC: UniProt records ubiquitination sites on it; ubiquitination databases record sites on it; its protein half-life has been measured.
Target class: Enzyme; Transferase
Gene: Protein-coding gene on chromosome 11 (119,206,298 to 119,313,926, forward strand). Ensembl gene ENSG00000110395.
Subcellular location: Cytoplasm; Cell membrane; Cell projection, cilium; Golgi apparatus
Subcellular location (Human Protein Atlas): Cytosol; End piece; Mitotic spindle
Pathways (Reactome):
Signal Transduction: EGFR downregulation; Negative regulation of FGFR1 signaling; Negative regulation of FGFR2 signaling; Negative regulation of FGFR3 signaling; Negative regulation of FGFR4 signaling; Negative regulation of MET activity; PTK6 Regulates RTKs and Their Effectors AKT1 and DOK1; Regulation of KIT signaling; Spry regulation of FGF signaling; TGF-beta receptor signaling activates SMADs
Disease: Constitutive Signaling by EGFRvIII; Constitutive Signaling by Ligand-Responsive EGFR Cancer Variants; FLT3 signaling by CBL mutants; InlB-mediated entry of Listeria monocytogenes into host cell
Immune System: Interleukin-6 signaling; Negative regulation of FLT3; Regulation of signaling by CBL; Signaling by CSF1 (M-CSF) in myeloid cells
Vesicle-mediated transport: Cargo recognition for clathrin-mediated endocytosis; Clathrin-mediated endocytosis
Gene Ontology:
Molecular function: cadherin binding; ephrin receptor binding; protein binding; SH3 domain binding; ubiquitin protein ligase activity; receptor tyrosine kinase binding; ubiquitin-protein transferase activity; calcium ion binding; metal ion binding; phosphatidylinositol 3-kinase regulatory subunit binding; phosphotyrosine residue binding; protein kinase binding; protein tyrosine kinase binding
Biological process: negative regulation of apoptotic process; negative regulation of epidermal growth factor receptor signaling pathway; negative regulation of T cell activation; negative regulation of T cell receptor signaling pathway; positive regulation of phosphatidylinositol 3-kinase/protein kinase B signal transduction; positive regulation of receptor-mediated endocytosis; protein K63-linked ubiquitination; protein stabilization; protein ubiquitination; ubiquitin-dependent protein catabolic process; cytokine-mediated signaling pathway; positive regulation of epidermal growth factor receptor signaling pathway; regulation of platelet-derived growth factor receptor-alpha signaling pathway; signal transduction; symbiont entry into host cell; cell surface receptor signaling pathway; cellular response to hypoxia; cellular response to nerve growth factor stimulus; cellular response to platelet-derived growth factor stimulus; DNA damage response; male gonad development; mast cell degranulation; protein autoubiquitination; protein monoubiquitination; protein polyubiquitination; and 7 more
Cellular component: cilium; cytosol; Golgi apparatus; plasma membrane; flotillin complex; membrane raft; axon; cytoplasm; focal adhesion; growth cone; perinuclear region of cytoplasm
Genetic constraint (gnomAD): Loss-of-function variants: 40 observed, 83.67 expected, observed/expected ratio (o/e) 0.48, 90% interval 0.37 to 0.62. The upper end of that interval is the gene's LOEUF score, 0.62, which puts it in group 2 of 6, group 1 being the genes least tolerant of losing a copy. Missense variants: 920 observed, 1,072.2 expected, observed/expected ratio (o/e) 0.86, 90% interval 0.81 to 0.91. Synonymous variants: 394 observed, 406.23 expected, observed/expected ratio (o/e) 0.97, 90% interval 0.89 to 1.05.
Gene-disease validity (ClinGen):
ClinGen rates the evidence that CBL causes each of these diseases.
CBL-related disorder (autosomal dominant): Definitive. CBL-related disorder is a genetic condition caused by pathogenic variants in the Cbl ubiquitin ligase gene, (CBL; HGNC:1541).
Cancer hallmarks: proliferative signalling (promotes); invasion and metastasis (promotes)
Homologues: Orthologues: chimpanzee CBL (100% identical), macaque CBL (99% identical), dog CBL (94% identical), pig CBL (94% identical), mouse Cbl (93% identical), rat Cbl (93% identical), guinea pig CBL (87% identical), rabbit CBL (87% identical), tropical clawed frog cbl (74% identical), zebrafish cbl (72% identical). Paralogues in human: CBLB (53% identical), CBLC (24% identical).
Diseases named in the same sentence as CBL in open-access papers:
CBL is named in the same sentence as 197 diseases in open-access papers, as found by Europe PMC text mining. Sharing a sentence is not in itself a finding about the gene and the disease. The quoted sentences say what the papers report.
breast carcinoma (38 papers, 2010 to 2024). "The loss of CBL reduces the ability of breast cancer cells to cause malignancy." (PMID 39130630, 2024). "miR-124-3p appears to be a tumor suppressorin breast cancer cells and it acts via targeting CBL (Cblproto-oncogene, E3 ubiquitin protein ligase).However, the molecular pathways underlying miR-124modulatory actions in breast cancer cells are notfully understood." (PMID 31606975, 2020). "So far, there are some studies suggesting that CBL is associated with breast cancer or TNBC." (PMID 30930932, 2019). "High CBL expression has actually been recognized as linked with the development of several types of cancer, including gliomas, gastric carcinoma, colorectal cancer, prostate cancer, breast cancer and non-small-cell lung cancer." (PMID 31976317, 2019). "An Alu insertion in an upstream enhancer of the CBL tumor suppressor gene is associated with down-regulation of the gene in a single breast cancer patient, and an L1 insertion in the first exon of the BAALC gene also disrupts its expression in head and neck squamous cell carcinoma." (PMID 27900322, 2016). "By controlling the H19-miR-675-5p-CBL axis, hurir extract reduced the viability of breast cancer cells and triggered apoptosis." (PMID 39130630, 2024). "The inhibitory effect of CBL-c on the proliferation, migration, and invasion of breast cancer cells was partially reversed by CTTN." (PMID 39130630, 2024). "CBL is significant in the therapy of breast cancer because it engages HIF-1 for ubiquitination in a proteasoma-dependent manner." (PMID 39130630, 2024). "The tumor-inhibitory activity of transforming growth factor (TGF) can be dramatically inhibited by the breast cancer cells with high CBL expression." (PMID 39130630, 2024). "By activating c-CBL and ERK to downregulate EZH2, YC-1 causes the apoptosis of breast cancer cells and reduces tumor development." (PMID 39130630, 2024). "On the other hand, node i is colored red because ubiquitin ligase CBL is deregulated in breast cancer." (PMID 35601606, 2022). "Recently, miR-124-3p.1 has been reported to function as a tumor suppressor in breast cancer by targeting CBL." (PMID 35013144, 2022). "We found that CBL interactions were predominantly distributed in two distinct subsets of breast cancer and DG75 signaling pathways." (PMID 33670716, 2021). "Given that CIN85 and CBL have been implicated in the invasiveness of breast cancer cells, we examined the expression of CIN85, CBL and Tyr371-phosphorylated CBL (pCBL) in human breast cancer tissue samples." (PMID 33627783, 2021). "We found a stage-wise increase in the expression levels of both CIN85 and CBL in breast cancer samples." (PMID 33627783, 2021). "This inverse relationship between CBL expression and its Tyr371-phosphorylation status implies that in the advanced stages of breast cancer the high levels of CBL remain in an E3-inactivated state in which CBL mainly functions as an adaptor." (PMID 33627783, 2021). "Given the importance of CBL and CIN85 in cancer progression of breast cancer cells and tissues, we investigated their association in breast cancer tissue microarrays through immunohistochemistry." (PMID 33627783, 2021). "CBL over-expression results in inhibition of transforming growth factor tumor suppressor activity and breast cancer prognosis." (PMID 32139710, 2020). "Downstream signaling regulating cell adhesion and invasion in breast cancer cells involves the CBL-dependent phosphorylation of ABL20." (PMID 28262839, 2017). "Overall, the findings of this study demonstrated that CBL is overexpressed in human breast cancer tissues and that the aberrant expression of CBL is responsible for the malignant behaviors of breast cancer cells." (PMID 27842510, 2016). "Quantitative RT-PCR and western blotting assays were used to measure miR-124-3p and CBL expression levels in breast cancer tissues, respectively." (PMID 27842510, 2016).
breast carcinoma (continued). "To further validate the correlation between miR-124-3p and CBL, we overexpressed or knocked down miR-124-3p in MCF-7 and MDA-MB-231 breast cancer cell lines and assessed the protein levels of CBL." (PMID 27842510, 2016). "Overall, this study demonstrates that miR-124-3p possesses tumor suppressor activity by negatively regulating CBL expression in breast cancer." (PMID 27842510, 2016). "By measuring CBL protein levels in the same 10 pairs of breast cancer tissues and normal adjacent tissues, we found that CBL was consistently upregulated in the breast cancer tissues." (PMID 27842510, 2016). "Cell proliferation and invasion assays were performed to analyze the biological functions of miR-124-3p and CBL in breast cancer cells." (PMID 27842510, 2016). "Among the candidates, CBL, an oncogene that is frequently observed to be upregulated in breast cancer, was selected and further investigated." (PMID 27842510, 2016). "This study identified a new regulatory axis in which miR-124-3p and CBL regulate the proliferation and invasion of breast cancer cells." (PMID 27842510, 2016). "Because CBL is well known to promote tumor proliferation and invasion, we examined if miR-124-3p would modulate CBL to influence the proliferation and invasion of breast cancer cells." (PMID 27842510, 2016). "Previously, we showed that tyrosine phosphorylation (Tyr774) of the adaptor protein c-CBL located downstream of EGFR in the ubiquitination cascade was slightly increased in breast cancer cells shortly after exposure to compound NSC." (PMID 27187356, 2016). "We also evaluated the effects of miR-124-3p-mediated suppression of CBL expression on the invasion of breast cancer cells using the Transwell invasion assay." (PMID 27842510, 2016). "It has been previously shown that activating c-CBL mutation downregulates EGFR signaling and decreases cellular proliferation and migration in breast cancer cell lines." (PMID 20126411, 2010). "CBL has an inhibitory effect on the proliferation and migration of breast cancer cells." (PMID 39130630, 2024). "In breast cancer, miR-124-3p ameliorated the malignancy of tumor via down-regulating CBL." (PMID 33954256, 2021). "Furthermore, we show that a peptide mimicking the proline-rich region of CBL that binds CIN85 reduces the proliferation of breast cancer cells." (PMID 33627783, 2021). "MiR-124-3p has been shown to be vital for HDAC-mediated C-EBPα initiation in HCC and may act as tumor-suppressor via targeting CBL in breast cancer." (PMID 33094104, 2020). "Thus, CBL was selected as a target of miR-124-3p, based on both computational predictions and their inverse correlation in breast cancer tissues." (PMID 27842510, 2016). "Furthermore, the molecular mechanism accounting for the aberrant upregulation of CBL in breast cancer was investigated." (PMID 27842510, 2016). "We next examined if miR-124-3p had expression patterns that are opposite to CBL in breast cancer." (PMID 27842510, 2016). "In summary, miR-124-3p might suppress the proliferation and invasion ability of breast cancer cells by targeting CBL." (PMID 27842510, 2016). "Moreover, we found that ectopic expression of CBL can attenuate the inhibitory effect of miR-124-3p on cell proliferation and invasion in breast cancer cells." (PMID 27842510, 2016). "Therefore, the modulation of CBL by miR-124-3p may explain why the downregulation of miR-124-3p can promote the development of breast cancer." (PMID 27842510, 2016). "Furthermore, we showed that miR-124-3p could suppress CBL expression and negatively regulate the proliferation and invasion of breast cancer cells." (PMID 27842510, 2016). "CDC42 and c-CBL are the critical components involved in the regulation of EGFR protein levels, and restoring proper EGFR degradation by disrupting the regulation of c-CBL by CDC42 can effectively reduce the proliferation and migration of breast cancer cells." (PMID 39130630, 2024).
breast carcinoma (continued). "CDC42 is frequently overexpressed in many cases of breast cancer, and evidence suggests that activated CDC42 enhances the accumulation of ErbB1 within cells by modulating the function of c-CBL." (PMID 39130630, 2024). "In human breast cancer samples, we found a correlation between levels of CIN85 and E3-inactivated CBL." (PMID 33627783, 2021). "We found that specific genes such as CBL, RHOA, EP300, RAC1, CDK1, and CDH1 are involved in the migration and invasion of breast cancer." (PMID 30930932, 2019). "Mechanistic studies revealed that miR-124-3p directly binds the CBL 3’-UTR and inhibit CBL expression, and that CBL overexpression sufficiently attenuates the inhibitory effects of miR-124-3p on breast cancer cell proliferation and invasion." (PMID 27842510, 2016). "In another study, it was discovered that the REDOX/Fyn/c-CBL (RFC) pathway, which typically translates the slight increase in oxidation into the accelerated degradation of c-CBL target proteins, was inhibited by Cdc42 in basal-like breast cancer (BLBC) cells." (PMID 39130630, 2024). "The findings imply that CIN85 and CBL, two well-known growth factor receptor signaling inhibitors, may be actively involved in tumor invasion and that the role of AMAP1 in breast cancer cell invasion is mediated by intricate epigenetic mechanisms." (PMID 39130630, 2024). "Conversely, CBL expression in the tumor positively correlates with survival in patients with metastatic colorectal cancer, and its CBLB homologue predicts better prognosis in breast cancer." (PMID 33670716, 2021). "This suggests that although there is a high level of CBL expression in advanced stages of breast cancer, its E3 ligase function is not activated." (PMID 33627783, 2021). "Under these circumstances, CBL could in principle act as an adaptor and recruit other proteins such as CIN85 to facilitate breast cancer progression." (PMID 33627783, 2021). "In addition, we investigated the molecular mechanism through which miR-124-3p contributes to breast cancer tumorigenesis and identified CBL (Cbl proto-oncogene, E3 ubiquitin protein ligase) as a direct target gene of miR-124-3p." (PMID 27842510, 2016). "Interestingly, pCBL shows an inverse correlation with both CIN85 and CBL, suggesting that high expression of inactivated CBL could coordinate with CIN85 for breast cancer progression." (PMID 33627783, 2021). "Thus, in advanced stages of breast cancer, CIN85 and CBL could coordinate to promote cancer progression and metastasis." (PMID 33627783, 2021). "In breast cancer, the expression profile of CBL has not been systematically investigated and the precise function of this gene remains unclear." (PMID 27842510, 2016). "Consequently, CBL protein levels were decreased in MCF-7 and MBA-MD-231 cells by the introduction of miR-124-3p, while the antisense of miR-124-3p significantly increased the CBL protein levels in these two breast cancer cell lines." (PMID 27842510, 2016).